RN7SL363P (RNA, 7SL, cytoplasmic 363, pseudogene)
Gene: Miscellaneous RNA gene on chromosome 15 (90,855,935 to 90,856,207, reverse strand). Ensembl gene ENSG00000241869.
Homologues: Orthologues: chimpanzee Metazoa_SRP (99% identical), macaque Metazoa_SRP (96% identical). Paralogues in human: RN7SL2 (84% identical), RN7SL1 (83% identical), RN7SL3 (82% identical), RN7SL336P (81% identical), RN7SL45P (81% identical), RN7SL220P (81% identical), RN7SL608P (81% identical), RN7SL398P (81% identical), RN7SL127P (80% identical), RN7SL444P (80% identical), RN7SL57P (80% identical), RN7SL665P (80% identical), and 705 more.